TOP2A (DNA topoisomerase II alpha)
Diseases named in the same sentence as TOP2A in open-access papers (continued):
Sharing a sentence is not in itself a finding about the gene and the disease.
lung adenocarcinoma (29 papers, 2017 to 2024). A carcinoma that arises from the lung and is characterized by the presence of malignant glandular epithelial cells. "In EGFRm lung adenocarcinoma, high TOP2A expression was also significantly associated with reduced OS." (PMID 38451729, 2024). "Study revealed that TOP2A was highly expressed in lung adenocarcinoma compared with matched adjacent normal tissues, and high expression of TOP2A was associated with poor prognosis for patients with LUAD." (PMID 38091511, 2022). "Our results showed that high TOP2A expression in lung adenocarcinoma, and the expression level of TOP2A was inversely associated with the prognosis of patients with LUAD." (PMID 32201520, 2020). "In addition, TOP2A has been associated with poor prognosis in cancers such as medulloblastoma and lung adenocarcinoma." (PMID 38661103, 2024). "Moreover, it has been shown that TOP2A expression is upregulated in lung adenocarcinoma patients and is associated with a poor prognosis." (PMID 33737587, 2021). "Also, on Cox proportional Hazards regression analysis, TOP2A expression in lung adenocarcinoma was an important risk factor for overall survival (hazard ratio (HR), 2.903; 95% confidence interval (CI), 1.019-4.299; P = 0.044) between low and high expression of TOP2A groups." (PMID 32201520, 2020). "Studies have shown that TOP2A has a high level of expression in lung adenocarcinoma and is related to poor prognosis." (PMID 38556560, 2024). "TOP2A facilitates the progression of lung adenocarcinoma cells and predicts the adverse prognosis of lung adenocarcinoma." (PMID 37980167, 2023). "TOP2A can promote the malignant progression of lung adenocarcinoma cells and predict the poor prognosis of lung adenocarcinoma." (PMID 36233060, 2022). "Our study aims to investigate the prognostic effect of TOP2A on lung adenocarcinoma (LUAD) and the potential molecular mechanism of TOP2A to tumorigenesis." (PMID 32201520, 2020). "Firstly, we explored the expression level of TOP2A in human lung adenocarcinoma cells (A549, LTEP-A2 and GLC82) and normal human bronchial epithelium cell (BEAS-2B)." (PMID 32201520, 2020). "This study was conducted to investigate TOP2A expression level, prognostic value in lung adenocarcinoma and the mechanism of proliferation and invasion." (PMID 32201520, 2020). "Meanwhile, multivariate COX regression analysis revealed that T stage, N stage and TOP2A expression work as independent prognostic factors in lung adenocarcinoma." (PMID 31528121, 2019). "And Multivariate Cox regression analysis supported TOP2A expression works as an independent prognostic indicator in lung adenocarcinoma, suggesting its probable tumor promoter and potential survival indicator function in further clinical use." (PMID 31528121, 2019). "TOP2A is also upregulated in lung adenocarcinoma, and it is related to poor patient prognosis." (PMID 36661515, 2023). "Besides, we determined the expression of TOP2A in 517 LUAD cases and 59 normal tissues in TCGA, which showed TOP2A was significantly highly expressed in lung adenocarcinoma." (PMID 32201520, 2020). "However, the biological function of TOP2A in lung adenocarcinoma was far from being thoroughly understood." (PMID 32201520, 2020). "Nevertheless, the role of TOP2A in lung adenocarcinoma remains poorly understood, whether TOP2A is a potentially significant prognostic indicator still needs to be investigated." (PMID 32201520, 2020). "Firstly, we examined the expression level of TOP2A in lung adenocarcinoma and normal tissues using bioinformatics analysis of GSE10072 (tumor = 58, normal =49), GSE43458 (tumor =80, normal = 30), GSE83213 (tumor = 11, normal =46) from GEO and TCGA (tumor = 517, normal =59)." (PMID 32201520, 2020). "Our findings suggest that TOP2A may not only be an effectively predictive and prognostic biomarker but also be a novel rationale for targeting TOP2A in the treatment of lung adenocarcinoma." (PMID 32201520, 2020).
lung adenocarcinoma (continued). "Initially, we evaluated the expression of TOP2A in lung adenocarcinoma." (PMID 32201520, 2020). "Additionally, qRT-PCR was conducted on 30 paired lung adenocarcinoma and squamous cell carcinoma samples of local hospital (different from the 107 samples used to make tissue array) to validate the relation between TOP2A and TPX2." (PMID 31528121, 2019). "Furthermore, the study showed that depleting FOXM1 expression decrease the TOP2A mRNA and protein level in A549 human lung adenocarcinoma cells." (PMID 31681566, 2019). "Like ANLN, TOP2A positively regulates invasion and migration and promotes EMT in lung adenocarcinoma, and in PC, TOP2A expression gives rise to enhanced cell proliferation, migration, and EMT." (PMID 34591244, 2021). "In addition, some potential target genes of the quercetin, such as TOP2A, CA4 and AURKB were related to the prognosis of lung adenocarcinoma patients." (PMID 36949111, 2023). "TOP2A and FAM83A are known to play a carcinogenesis role in lung adenocarcinoma." (PMID 37507593, 2023). "Whereas, the functional role of TOP2A and involving pathways in lung adenocarcinoma (LUAD) are not clear." (PMID 32201520, 2020). "Especially, high expression of two topoisomerase isoforms, TOP2A and TOP3A, was found to be correlated to worse overall survival (OS) in all NSCLC and lung adenocarcinoma (Ade) patients, but not in lung squamous cell carcinoma (SCC) patients." (PMID 28355294, 2017).
ovarian carcinoma (29 papers, 2010 to 2025). A malignant neoplasm originating from the surface ovarian epithelium. "To assess the impact of the C2 TOP2A+ TCs subgroup on the progression of ovarian cancer and patient outcomes, we developed a novel predictive model, the TOP2A TCs Risk Score (TTRS), through multivariate Cox analysis." (PMID 39136009, 2024). "Future investigations should involve multicenter studies with larger sample sizes to validate the roles of MYBL2 and the TOP2A TCs Risk Score in ovarian cancer." (PMID 39136009, 2024). "Prior studies have shown that mutations in the TOP2A gene have a significant effect on the outlook for individuals with ovarian cancer, with increased levels of TOP2A protein expression observed in ovarian cancer tissues." (PMID 39136009, 2024). "Various studies have shown the association between TOP2A and ovarian cancer; however, in-depth investigations about the mechanism of MYB in ovarian cancer remain scarce." (PMID 33407591, 2021). "In addition, TRRAP depletion leads to down‐regulation of TOP2A, which is consistent with our results and indicates that the association between these two genes is worthy of exploration in ovarian cancer." (PMID 35735060, 2022). "In conclusion, this study clarified the regulatory role of TOP2A in cisplatin resistance of ovarian cancer." (PMID 41235254, 2025). "Relationship between TOP2A protein expression and clinicopathological features of Epithelial ovarian cancer." (PMID 41235254, 2025). "The progression-free survival (PFS) curve of ovarian cancer (OV) patients in the high TOP2A expression group was significantly lower than that in the low TOP2A expression group." (PMID 41235254, 2025). "Among the four ovarian cancer subgroups identified, the C2 TOP2A+ TCs were potentially at the initial stage of differentiation and had not received neoadjuvant treatment." (PMID 39136009, 2024). "We have revealed the heightened susceptibility of the C2 TOP2A+ TCs subgroup to neoadjuvant chemotherapy and emphasized the role of MYBL2 within the C2 subgroup in promoting the occurrence and progression of ovarian cancer." (PMID 39136009, 2024). "This review provides a comprehensive overview of the current understanding of TOP2A’s role in ovarian cancer, highlighting its potential as a therapeutic target." (PMID 39727717, 2024). "In epithelial ovarian cancer (EOC), TOP2A overexpression is associated with poor prognosis and resistance to conventional treatments." (PMID 39727717, 2024). "This study underscores the importance of genetic profiling in improving treatment outcomes and highlights the potential of TOP2A as a predictor of response to PLD in ovarian cancer." (PMID 39727717, 2024). "Ovarian cancer patients with elevated TOP2A expression exhibited heightened sensitivity to neoadjuvant chemotherapy (NACT)." (PMID 39136009, 2024). "The protein expression levels of CCNA2, CCNB1, CDC20, CDCA8, CDK1, KIF11 and TOP2A were high in ovarian cancer tissues, which was further confirmed via the HPA database." (PMID 34253236, 2021). "It has also been indicated that TOP2A overexpression occurs in ovarian tumors: it is currently the main target of clinical trials of ovarian cancer therapies." (PMID 31756998, 2019). "Elevated TOP2A mRNA were observed in high grade ovarian cancers as well as advanced stage diseases, and patients with overexpression of nuclear TOP2A protein had a marked decreased OS." (PMID 27315793, 2016).
ovarian carcinoma (continued). "TOP2A has also been shown to be overexpressed in ovarian tumours and is currently a common target in ovarian cancer clinical trials." (PMID 22452920, 2012). "DNA topoisomerase IIα (TOP2A) relates to cancer drug resistance, yet its role and molecular mechanisms in ovarian cancer cisplatin resistance remain unclear." (PMID 41235254, 2025). "However, current studies on the specific functional role and molecular mechanisms of TOP2A in cisplatin resistance of ovarian cancer remain in the preliminary exploration stage." (PMID 41235254, 2025). "Therefore, the C2 TOP2A+ TCs subgroup appears to be intricately involved in the progression of ovarian cancer." (PMID 39136009, 2024). "In addition, TOP2A is upregulated in various tumors such as colon and ovarian malignant tumors and can be used as a sensitive biomarker for early detection and treatment of these tumors." (PMID 35190747, 2022). "It was found that TOP2A, ANXA5, and LRRN4 were associated with ovarian cancer survival prognosis." (PMID 32368301, 2020). "TOP2A can play an important prognostic role in epithelial ovarian cancer (EOC)." (PMID 31756998, 2019). "TOP2A (P4) is also associated with rapidly progressing cancers and relatively poor survival while EDDR1 (P15), a protein receptor kinase found to be over-expressed in ovarian cancers, is associated with poor prognosis and overall survival." (PMID 22862954, 2012). "Therefore, NACT could potentially yield better outcomes in ovarian cancer patients exhibiting high TOP2A expression." (PMID 39136009, 2024). "This suggests a close correlation between high TOP2A expression and shorter PFS in ovarian cancer patients." (PMID 41235254, 2025). "Results from the PPI network revealed that the KIT, TOP2A, and MYB genes exhibited a higher correlation with other genes, and were thus likely to affect the development of ovarian cancer." (PMID 33407591, 2021). "Additionally, TOP2A is a direct molecular target of topoisomerase inhibitor, and its upregulation has been reported in several cancers including lung, nasopharyngeal, esophageal, gallbladder, hepatocellular, colorectal, breast, endometrial, pancreatic and ovarian cancer." (PMID 30453999, 2018). "The protein expressions of 5 hub genes (CDK1, TOP2A, CDC20, NCAPG, and MELK) are significantly up-regulated in ovarian cancer compared to normal tissues." (PMID 30453999, 2018). "A recent study has identified that DLX4, frequently overexpressed in breast and ovarian cancers, stimulates repair of DNA DSB induced by TOP2A poisons, thereby decreasing cell sensitivity to the treatment." (PMID 26560244, 2015). "Atleast three antigens (P4, P5 and P15, representing peptides from topoisomerase IIa (TOP2A), Integrin β8-precursor, and EDDR1 respectively) have been demonstrated to be upregulated at the mRNA level in ovarian cancer (unpublished observations)." (PMID 22862954, 2012). "Moreover, the heat map for the expression patterns of the first 150 DEGs in GSE4122 was plotted, which revealed that TOP2A and MYB were highly-expressed in ovarian cancer." (PMID 33407591, 2021). "Based on GO functional analysis, KEGG pathway analysis, and survival analysis, we found that CDK1, TOP2A, and UBE2C might be the core genes contributing to the development of epithelial ovarian cancer at the molecular level." (PMID 30453999, 2018). "The findings suggest that TOP2A could serve as a valuable biomarker to identify patients who are more likely to benefit from PLD treatment, thus helping in the personalization of therapeutic strategies for ovarian cancer." (PMID 39727717, 2024). "Moreover, our meta-analysis identified three specific genes, namely, CDK1, TOP2A and UBE2C, which may be potential targets of ovarian cancer." (PMID 30453999, 2018).
cervical cancer (27 papers, 2013 to 2025). A primary or metastatic malignant neoplasm involving the cervix. "This study provides a theoretical basis for miR‐320a as a potential marker for diagnosing CC infected with HPV16 E6 and miR‐320a/TOP2A axis as a potential target for the treatment of cervical cancer caused by HPV infection." (PMID 38205938, 2024). "Diagnostic values of p16 and TOP2A immunohistochemistry in differentiating cancerous cervical lesions from benign and precancerous cervical lesions among women seeking cervical cancer care at Kilimanjaro Christian Medical Centre (n = 139)." (PMID 34705880, 2021). "Overall, our findings support the associations of p16 and TOP2A biomarkers in the development of cervical cancer lesions." (PMID 34705880, 2021). "MCM2 and TOP2A, which have been widely reported as associated with cervical cancer, ranked 15th and 18th on the list, respectively." (PMID 23405241, 2013). "Multivariate regression analysis and the strength of association between expression levels of p16 and TOP2A in differentiating cancerous cervical lesions from benign and precancerous cervical lesions among women seeking cervical cancer care at Kilimanjaro Christian Medical Centre (n = 139)." (PMID 34705880, 2021). "In one study, Wang and co-authors observed an aberrant upregulation of TOP2A in cervical cancer tissues through experimental investigations (transwell invasion and migration, and Western blotting)." (PMID 38730579, 2024). "It was reported that the expression of TOP2A was up-regulated in cervical cancer and it promoted cell migration, invasion and epithelial-mesenchymal transition in cervical cancer by activating the PI3K/AKT signaling." (PMID 39060960, 2024). "TOP2A expression is positively correlated with cervical cancer and is overexpressed in many human malignancies." (PMID 37509353, 2023). "TOP2A promotes cervical cancer cell migration, invasion, and epithelial-mesenchymal transition (EMT) via activating the phosphatidylinositol-3-kinase (PI3K)/V-akt murine thymoma viral oncogene homolog (AKT) signal." (PMID 35012441, 2022). "Emerging studies have delineated that TOP2A is aberrantly expressed in various solid tumors, including cervical cancer, bladder urothelial carcinoma, and lung adenocarcinoma." (PMID 35012441, 2022). "These cellular biomarkers (p16 and TOP2A) are emerging as novel biomarkers for early diagnosis and prognosis of cervical cancer." (PMID 34705880, 2021). "The age-adjusted odds ratio for predicting cervical cancer lesions were independently significant for p16/TOP2A biomarkers in FFPE cervical tissues [p16: OR = 1.142 (95% CI: 1.059–1.232, p<0.001) and TOP2A: OR = 1.046 (95% CI: 1.008–1.085, p = 0.015)]." (PMID 34705880, 2021). "Survival analysis was performed on the top 10 genes with protein-protein interactions showed that the overall survival (OS) time of CDC45, RFC4 and TOP2A was significantly correlated with the prognosis of cervical cancer." (PMID 34557356, 2021). "In contrary, there was significant association between histopathological class and expression levels of p16 and TOP2A among women seeking cervical cancer care (p<0.001)." (PMID 34705880, 2021). "Correlation matrix for p16 and TOP2A biomarkers expression with the histopathological factors among women seeking cervical cancer care at Kilimanjaro Christian Medical Centre (n = 139)." (PMID 34705880, 2021). "Expression levels of p16 and TOP2A biomarkers have been reported for early diagnosis of cervical cancer in high-resource countries, which necessitates the need for their feasibility study in low-resource settings." (PMID 34705880, 2021). "TOP2A is overexpressed during the progression from cervical intraepithelial neoplasia 2 (CIN2)-CIN3 to cervical cancer, and thus it is considered to be a late marker of cervical carcinogenesis." (PMID 27175798, 2016).